NEK2 (NIMA related kinase 2)
Diseases named in the same sentence as NEK2 in open-access papers (continued):
Sharing a sentence is not in itself a finding about the gene and the disease.
gastric cancer (18 papers, 2020 to 2025). A primary or metastatic malignant neoplasm involving the stomach. "This study established the association between NEK2 and ferroptosis for the first time, further enriching the mechanism of ferroptosis in gastric cancer." (PMID 38503948, 2025). "It was also found that ERK is functionally associated with NEK2 expression and knockdown of NEK2 inhibits ERK phosphorylation in gastric cancer cells." (PMID 35711835, 2022). "Preliminary studies have shown that NEK2 plays a oncogene role in gastric cancer, and our previous studies have found that NEK2 was highly expressed in gastric cancer tissues and suggested that patients have a worse prognosis." (PMID 38503948, 2025). "Both the mRNA and protein levels of NEK2 are significantly upregulated in gastric cancer (GC) as compared to normal stomach samples." (PMID 40076620, 2025). "This study found that inhibiting NEK2 can increase the ferroptosis sensitivity of gastric cancer cells, and enrich the mechanism of NEK2 in gastric cancer." (PMID 38503948, 2025). "It is suggested that inhibiting NEK2 to promote HMOX1 transcription through Keap1/Nrf2 was an important mechanism to affect ferroptosis in gastric cancer cells." (PMID 38503948, 2025). "Our previous studies have found that NEK2 is highly expressed in gastric cancer and suggests that patients have a worse prognosis." (PMID 38503948, 2025). "Nek2, a member of the same family as Nek6, was reported to inhibit autophagy in gastric cancer via activating protein kinase B (Akt)/mammalian target of rapamycin (mTOR) signaling pathway." (PMID 39702325, 2024). "Nek2, which belongs to the same family as Nek6, has been reported to inhibit autophagy in gastric cancer via activating AKT signaling pathway." (PMID 39702325, 2024). "NEK2 has been demonstrated to inhibit gastric cancer cells proliferation, migration and tumor growth by activating the KDM5B/H3K4me3 signaling pathway." (PMID 37233832, 2023). "For example, it has been proven that circPDSS1 is conducive to gastric cancer progression via sequestering miR-186-5p and regulating NEK2." (PMID 35902921, 2022). "CircPDSS1 is a novel circRNA in cancer research and has been reported to facilitate gastric cancer development via binding with miR-186-5p and modulating NEK2." (PMID 35902921, 2022). "In this study, it was found that inhibiting NEK2 could increase the ferroptosis sensitivity of gastric cancer cells." (PMID 38503948, 2025). "To determine whether inhibition of NEK2 affects the ferroptosis sensitivity of gastric cancer cells, we knockdown NEK2 expression and induced ferroptosis in AGS cell line." (PMID 38503948, 2025). "Therefore, there are few studies on the mechanism of action of NEK2 in gastric cancer, which is one of the key factors limiting the development of therapeutic strategies targeting NEK2." (PMID 38503948, 2025). "In order to reveal the mechanism of NEK2 knockdown enhanced the ferroptosis sensitivity of gastric cancer cells, we analyzed the differentially expressed genes in samples after inhibiting NEK2 based on RNA-seq, and screened differentially expressed genes by setting the |log2FC| ≥ 1&q value < 0.05." (PMID 38503948, 2025). "The expression level of NEK2 in human gastric cancer (GC) tissues is significantly upregulated." (PMID 35646063, 2022). "However, whether NEK2 regulates the process of ferroptosis and thus affects gastric cancer cells is unknown." (PMID 38503948, 2025). "The results showed that inhibiting NEK2 expression increased HMOX1 mRNA and protein levels in gastric cancer cells, consistent with the results of RNA-seq, while CHAC1 levels did not change." (PMID 38503948, 2025). "For instance, a recent study demonstrated that NEK2 regulated the expression of KDM5B/H3K4me3 through β-catenin/Myc, resulting in the promotion on cell proliferation, migration, and tumor growth of gastric cancer." (PMID 35031599, 2022).
gastric cancer (continued). "Nek2 can regulate the ERK/MAPK pathway, thus promoting the proliferation of gastric cancer cells and the development of gastric cancer." (PMID 35935324, 2022). "In this study, the results of the bioinformatic analysis showed that among NEKs, the expressions of NEK2, NEK6, and NEK7 are upregulated, whereas NEK3 and NEK7 are related to the poor prognosis of gastric cancer." (PMID 34419048, 2021). "Mechanism studies have found that inhibiting NEK2 could promote the expression of HMOX1, a gene related to ferroptosis, and enhance the sensitivity of gastric cancer cells to ferroptosis by increasing HMOX1." (PMID 38503948, 2025). "Combined with the previous results, it was shown that inhibiting NEK2 could promote the expression of HMOX1 through Keap1/Nrf2, enhance the ferroptosis sensitivity of gastric cancer cells, and further affect the cell biological function." (PMID 38503948, 2025).
ovarian carcinoma (17 papers, 2014 to 2025). A malignant neoplasm originating from the surface ovarian epithelium. "On the basis of differentially expressed genes (DEGs) identified through the Gene Expression Omnibus (GEO) portal, it was found that elevated NEK2 gene expression was linked to drug resistance in ovarian cancer, compared to the parental counterparts." (PMID 34072728, 2021). "Drug resistance in ovarian cancer is associated with the upregulation of NEK2, along with that it is an oncogene whose activation leads to the development of cancer hence targeting its activity becomes crucial." (PMID 34072728, 2021). "It was found that circTNPO3 was highly expressed in resistant ovarian cancer cell lines and tissues, and facilitated paclitaxel chemoresistance via miR-1299/NEK2 axis." (PMID 40822457, 2025). "Although this study suggests a disease-promoting role for NEK2 in ovarian cancer, the KMPlot data demonstrate a conflicting view by showing a beneficial hazard ratio for patients with higher NEK2 levels." (PMID 37046733, 2023). "The role circTNPO3 plays in the carcinogenesis of ovarian cancer is to promote PTX resistance in ovarian cancer cells by upregulating NEK2 expression via sponge miR-1299." (PMID 34445958, 2021). "The TTK, NEK2, and CDK1 are over-expressed, demonstrating a high frequency of genetic alterations, and are associated with poor prognosis of ovarian cancer cohorts." (PMID 34072728, 2021). "For example NEK2 inhibitors have been developed as possible chemotherapeutic interventions because NEK2 is overexpressed in several different cancer, including breast and ovarian cancers." (PMID 25290377, 2014). "In conclusion, TTK, NEK2, and CDK1 are strongly associated with tumorigenesis, therapeutic resistance, and poor prognosis of ovarian carcinoma and thus serve as a novel biomarker for diagnosis as well as attractive therapeutic targets for the treatment of ovarian carcinoma." (PMID 34072728, 2021). "In ovarian cancer, Nek2 induces drug resistance by regulating the cell cycle and microtubules." (PMID 31319849, 2019). "CircTNPO3 could decoy miR-1299 and upregulate NEK2 (NIMA-related kinase 2) in ovarian cancer." (PMID 38152652, 2023). "The topmost ranked genes uncovered for the PD doublets include CDCA3, PLK1, NEK2 and FAM64A, which are involved in ovarian cancer cell proliferation and drug resistance." (PMID 40280979, 2025). "The Oncomine database was used for the expression analysis of TTK, NEK2, and CDK1 in ovarian cancer and normal samples." (PMID 34072728, 2021). "To investigate the roles of TTK, NEK2, and CDK1 overexpression, we mined the TCGA’s ovarian cancer genomics data via the cBioportal website." (PMID 34072728, 2021). "The HPA database was used to verify histological levels of TTK, NEK2, and CDK1, and results suggested that TTK, NEK2, and CDK1 were upregulated in ovarian cancer tissue compared to the normal tissue." (PMID 34072728, 2021). "We have earlier reported NSC777201 for some biological activities, herein, we used a molecular docking approach and an NCI’s ovarian cancer cell lines to evaluate its anti-cancer activity and explore its possibility for targeting TTK, NEK2, and CDK1." (PMID 34072728, 2021). "Collectively, our study suggested that TTK, NEK2, and CDK1 are novel biomarker signatures of ovarian carcinoma and an attractive target for NSC777201 with consequent anticancer implications." (PMID 34072728, 2021). "CircTNPO3 increases the expression of NIMA-related kinase 2 (NEK2) by directly targeting miR-1299, which then contributes to chemotherapeutic resistance in ovarian cancer." (PMID 34660304, 2021). "Role of NEK2, CCNA2, and AURKA as potential targets in ovarian cancer has been recently highlighted by a detailed systematic bioinformatic study." (PMID 26992853, 2016). "In addition to the PPI network, ingenuity pathway analysis also implicate TTK, NEK2, and CDK1 in the elevated salvage pyrimidine and pyridoxal pathways in ovarian cancer." (PMID 34072728, 2021).
ovarian carcinoma (continued). "Furthermore, we used the GEPIA web-based tool to investigate the roles of these genes in ovarian cancer; interestingly, we found that expressions of TTK, NEK2, and CDK1 were correlated with tumor stages." (PMID 34072728, 2021). "NSC777201 demonstrated antiproliferative and dose-dependent anticancer activity against the NCI’s ovarian cancer cell lines, and its further evaluation towards TTK, NEK2, and CDK1 inhibition was carried out with in silico docking in a receptor-ligand interaction study." (PMID 34072728, 2021).
glioma (15 papers, 2014 to 2024). A benign or malignant brain and spinal cord tumor that arises from glial cells (astrocytes, oligodendrocytes, ependymal cells). "NEK2 is widely upregulated in gliomas and associated with WHO grades, proliferation, and prognosis in malignant gliomas." (PMID 33995499, 2021). "Nek2 overexpression was shown to confer an inferior survival in gliomas and it is associated with drug resistance and cell proliferation in several types of cancer." (PMID 25365520, 2014). "Shortly, deficiency of circPITX1 blocked tumor growth of glioma via miR-329-3p/NEK2 axis." (PMID 32190004, 2020). "In summary, NEK2 showed significantly differential expression in correlation with malignant progress of glioma." (PMID 35031599, 2022). "To confirm the existence of the regulatory axis circPITX1/miR-329-3p/NEK2 in glioma, we tried to clarify the effect of circPITX1 on NEK2 level." (PMID 32190004, 2020). "A significant positive correlation between the expression of circPITX1 and NEK2 in glioma tissues was confirmed by Pearson correlation analysis." (PMID 32190004, 2020). "CircPITX1 knockdown reduced glycolysis to contribute to radiosensitivity in glioma through miR-329-3p/NEK2 axis, providing a possible mechanism of circPITX1 in the development of glioma." (PMID 32190004, 2020). "Silence of circPITX1 inhibited glycolysis to enhance radiosensitivity in glioma by regulating miR-329-3p/NEK2 axis." (PMID 32190004, 2020). "MiR-329-3p exerted inhibitory effects on glycolysis and radioresistance of glioma cells by targeting NEK2." (PMID 32190004, 2020). "Then, we transfected glioma cells or mutant hsa‐mir‐346 mimics and luciferase‐labelled NEK2‐3'UTR with hsa‐mir‐346, which were subjected to luciferase reporter gene analysis." (PMID 32449290, 2020). "What’s more, we found that NEK2 mRNA was up-regulated in glioma tissues when compared with normal tissues, and was negatively correlated with miR-329-3p expression in glioma tissues." (PMID 32190004, 2020). "Other evidence indicated that NEK2 promoted glioma stem cell radioresistance through the regulation of EZH2." (PMID 32503578, 2020). "MTT assay uncovered that miR-329-3p evidently retarded cell viability of glioma cells, while overexpression of NEK2 ameliorated the inhibition." (PMID 32190004, 2020). "A former study revealed that NEK2 expression was enriched in glioma, and targeted by miR-128 to modulate the apoptosis of glioma cells." (PMID 32190004, 2020). "We also identified the up-regulation of NEK2 in glioma U251 and LN229 cells versus NHA, at mRNA and protein levels." (PMID 32190004, 2020). "Expression of circPITX1 and NEK2 was up-regulated in glioma tissues and cells, while miR-329-3p exhibited reverse trend." (PMID 32190004, 2020). "In glioma, NEK2 has been suggested to be correlated with malignancy and the poor overall survival of patients with glioma." (PMID 32190004, 2020). "Downregulation of miR-128 expression by targeting NEK2 reduced glioma cell death." (PMID 36793341, 2022). "Moreover, we identified that elevated NEK2 expression was closely related to poor prognosis in glioma patients." (PMID 35031599, 2022). "Furthermore, Kaplan-Meier survival analysis from TCGA datasets demonstrated that glioma patients with higher expression of NEK2 exhibited a shorter overall survival." (PMID 35031599, 2022). "The results indicated that NEK2 was overexpressed in GBM compared with low-grade glioma." (PMID 35031599, 2022). "However, Nek2 is overexpressed in many cancers, including those of the liver, lungs, pancreas, glioma, colon, prostate, and breast." (PMID 36494865, 2022). "Moreover, in glioma cells, s-μg inhibited FAK, reduced RhoA/Rock signalling and Nek2 expression, and attenuated glioma viability and migration." (PMID 35052703, 2021). "As expected, NEK2 protein level was also higher in glioma tissues in reference to normal tissues." (PMID 32190004, 2020).
glioma (continued). "In short, up-regulation of NEK2 could relieve the repressed effects of miR-329-3p on the glycolysis and radioresistance of glioma U251 and LN229 cells." (PMID 32190004, 2020). "Likewise, NEK2 was up-regulated in glioma tissues and cells, at both mRNA and protein levels." (PMID 32190004, 2020). "Here, we intended to clarify whether NEK2 was involved in circPITX1-mediated glioma progression." (PMID 32190004, 2020). "We found an overexpression of DLGAP5, NEK2, and PBK, while the expression of SF1, PTEN, ATRX, and DAXX was downregulated in tumor tissues as compared to normal tissues of the patients with glioma." (PMID 35095717, 2021). "Recently, four groups reported different circPITX1-mediated ceRNETs in glioma cells, i.e., circPITX1/miR-518a-5p/IL17RD, circPITX1/miR-1304/ERBB4, circPITX1/miR-379-5p/mitogen-activated protein kinase 2 (MAP3K2), and circPITX1/miR-329-3p/NIMA-related kinase 2 (NEK2)." (PMID 33995499, 2021).
prostate carcinoma (14 papers, 2013 to 2025). A carcinoma that arises from epithelial cells of the prostate gland. "However, whether aberrant expression of NEK2 is associated with outcome of prostate cancer (PCa) patients remains to be determined." (PMID 26320076, 2015). "MiR-1299 transcriptionally repressed NEK2 in prostate cancer cells, attenuating the proliferation, invasion and migration." (PMID 39768163, 2024). "In prostate cancer, overexpression of NEK2 contributes to the proliferation and tumorigenicity of LNCaP cells, and is correlated to the poor prognosis of patients with prostate cancer." (PMID 32190004, 2020). "Compelling data indicates high levels of the centrosomal kinase Nek2 protein in cell lines derived from breast, cervical, and prostate carcinomas." (PMID 23776583, 2013). "Furthermore, the role of NEK2 has been reported in the migration and invasion of diverse cancer cell lines, including breast, colorectal, liver, lung, and prostate cancer cell." (PMID 39768163, 2024). "The high expression of NEK2 has also been identified in prostate cancer." (PMID 34834441, 2021). "NEK2, is also related to progression and poor prognosis in prostate cancer." (PMID 31906878, 2020). "In silico analyses of the online Taylor dataset were carried out to determine whether the expression level of NEK2 correlated with the clinicopathological characteristics of prostate cancer." (PMID 26320076, 2015). "Transcriptome analyses of prostate cancer samples, benign, prostatic hyperplasia, and normal tissue, revealed, NEK5 and NEK2 are over-expressed in malignant tissue." (PMID 31906878, 2020). "Our analysis further identified the mitotic kinase NEK2 and stem cell transcription factor SOX9 as downstream targets of ALDH1, which might be involved in the development of multi-drug resistance in prostate cancer cells." (PMID 33339129, 2020).
triple-negative breast carcinoma (12 papers, 2013 to 2025). An invasive breast carcinoma which is negative for expression of estrogen receptor (ER), progesterone receptor (PR), and human epidermal growth factor receptor 2 (HER2). "A recent study showed that NEK2 interacts with riboprotein binding Sam68 in triple-negative breast cancer cells." (PMID 37900073, 2023). "Furthermore, overexpression of NEK2 in triple-negative breast cancer cells promotes cell migration and invasion." (PMID 36499051, 2022). "We performed immunohistochemical analysis of triple-negative breast cancer (TNBC) tissue microarrays and assessed the correlation between NEK2/TUFT1 expression and patient outcome." (PMID 41022752, 2025). "In addition, we tested a triple-negative breast cancer cell line of the basal subtype derived from human patients (Hs578T) as a second, physiologically relevant model to determine whether ciliation can be restored by modulating the Nek2–Kif24 pathway." (PMID 26290419, 2015). "NEK2 mediates the phosphorylation of SAM68 protein, thus stimulating splicing, indicating that NEK2 and SAM 68 work together in regulating splicing, which sustains the prometastatic features in triple-negative breast cancer cells." (PMID 37900073, 2023). "The purpose of our study was to determine whether drug sensitivity was increased in the triple negative breast cancer cell lines MDA-MB-231 and MDA-MB-468 by using small interfering RNA (siRNA) and antisense oligo-nucleotides (ASOs) against Nek2." (PMID 23340795, 2013).